ATF4 (activating transcription factor 4)
Diseases named in the same sentence as ATF4 in open-access papers (continued):
Sharing a sentence is not in itself a finding about the gene and the disease.
cardiac hypertrophy (8 papers, 2017 to 2025). "Specifically, the eIF2α‐ATF4‐CHOP pathway has been associated with the development of cardiac hypertrophy." (PMID 32189431, 2020). "By activating the PERK/ATF4 signaling pathway, Nogo-β is prevented, resulting in myocardial hypertrophy." (PMID 36703744, 2022). "In our study, the eIF2 signaling pathway was markedly elevated, consistent with previous reports of ER stress‐induced cardiac hypertrophy, suggesting that the eIF2α‐ATF4‐CHOP pathway is a probable pathway of disease in our HCM mice." (PMID 32189431, 2020). "The major endoplasmic reticulum stress signaling pathway causing cardiac hypertrophy involves endoplasmic reticulum stress sensor PERK (protein kinase-like kinase) and eIF2α-ATF4-CHOP signaling." (PMID 28743963, 2017). "Therefore, it is unlikely that ATF4, or even ER stress, are contributing to the development of cardiac hypertrophy in our model." (PMID 40301189, 2025). "To further identify the mechanism by which Aggf1 haploinsufficiency augments cardiac hypertrophy and heart failure, we analyzed CHOP and other ER stress signaling markers BiP, ERO1α, Puma, DR5, ATF4, cATF6, p-eIF2α, phosphorylated PERK (p-PERK), and sXBP1 using western blot analysis." (PMID 28743963, 2017). "However, our results rule out a role for ATF4, or even ER stress, in the development of cardiac hypertrophy in our model." (PMID 40301189, 2025).
colitis (8 papers, 2012 to 2025). Inflammation of the colon. "Furthermore, our results suggest that colitis-associated overexpression of Atf4 and Egr1 cannot be reversed by MM depletion and l-clodronate treatment." (PMID 38105266, 2023). "Conversely, blocking this pathway has been shown to reduce ERS and mitigate dextran sulfate sodium–induced colitis, and silencing ATF4 in vitro has been found to substantially opposed H/R-induced ERS and protected cells from H/R damage." (PMID 40248101, 2025). "Specifically, our findings indicate that LCN2 mediated the regulatory effect of ILC3s on colitis through the ATF4-xCT/GPX4 axis." (PMID 39300068, 2024). "Furthermore, previous research indicated that Prevotella copri (a member of Alloprevotella) exacerbates DSS-induced colitis in mice by downregulating ATF4 expression and altering the composition of intestinal microbiota." (PMID 39633810, 2024). "In this study, we used piroxicam to induce IL-10−/− mice to produce a chronic colitis model and explored whether JPQCD could regulate the PERK/eIF2α/ATF4/CHOP pathway, thus improving ER stress and preventing UC." (PMID 35186102, 2022). "However, the induction of colitis by TNBS resulted in significant increases in the mRNA levels of ATF6, ATF4, BiP and CHOP, both at 2 d and 7 d." (PMID 23209735, 2012). "Combining with the inhibitory effect of ARS on PERK- eIF2α-ATF4-CHOP and IRE1α-XBP1s signaling pathways, we speculated that the inhibitory effect of ARS on ER stress plays an important role in its anti-inflammatory effect on DSS-induced colitis." (PMID 33767628, 2021).
fibrosarcoma (8 papers, 2014 to 2025). A malignant mesenchymal fibroblastic neoplasm affecting the soft tissue and bone. "Our results are in agreement with previous research which shows that ATF4 induction in cancer cells contributes significantly to anoikis resistance in fibrosarcoma cells." (PMID 35847893, 2022). "In fibrosarcoma, ATF4 is induced upon detachment and suspension of cancer cell, and it is critical to protect cancer cells from anoikis." (PMID 34746012, 2021). "This important function of ATF4 makes it indispensable for successful colonization of fibrosarcoma cells in the lung of the mouse models." (PMID 34746012, 2021). "ATF4 governs amino acid synthesis and the oxidative stress response in mammalian cells and promotes the growth of fibrosarcoma." (PMID 25147208, 2014). "In addition, ATF4 was postulated to stimulate metastasis in human fibrosarcoma cells." (PMID 27802179, 2016). "To assess the general importance of the cooperative action of YAP/TAZ and ATF4 in overcoming ferroptosis in various cancer cell types, we have further addressed the roles of YAP/TAZ and ATF4 in HT1080 human fibrosarcoma cells in response to a variety of ferroptotic stimuli." (PMID 34664408, 2021). "Knockdown of DENR and/or eIF2D also reduced ATF4 protein levels in HT1080 fibrosarcoma cells indicating this is not specific to HeLa cells." (PMID 32938922, 2020).
ischemia (8 papers, 2010 to 2025). A hypoperfusion of the BLOOD through an organ or tissue caused by a PATHOLOGIC CONSTRICTION or obstruction of its BLOOD VESSELS, or an absence of BLOOD CIRCULATION. "The up-regulation of ATF4 has been associated with ischemia of both brain and spinal cord." (PMID 20534130, 2010). "On the other hand, ATF4 action is important in order to restore ER homeostasis in cardiomyocytes following ischemia." (PMID 36707786, 2023). "Results showed ischemia significantly increased the protein expression of p-PERK, p-eIF2α and ATF4 in the brain of MCAO mice." (PMID 29662437, 2018). "ATF4 mRNA and XBP1 mRNA, which were present in control rats and had increased markedly in the lungs which limbs underwent 4h of ischemia and 4h of reperfusion." (PMID 20148646, 2010). "Interestingly, during the initial stages of ischemia, rapid activation of the PERK/p-eIF2α/ATF4 pathway occurs, leading to the inhibition of protein synthesis and activation of genes involved in antioxidant defense through the selective translation of activating transcription factor 4 (ATF4)." (PMID 38251125, 2024).
renal carcinoma (8 papers, 2015 to 2025). A carcinoma arising from the epithelium of the renal parenchyma or the renal pelvis. "Taken together, the inhibition of FADS1 in renal cancer cells promoted ER stress via activating the PERK/eIF2α/ATF4 pathway, with ATF3 likely playing a key role in mediating this effect." (PMID 40121894, 2025). "In agreement with this, in cancer entities where ATF4 activity (assayed as ASNS mRNA levels) correlates with survival (e.g. renal cancer and liver hepatocellular carcinoma), also DENR or MCTS1 levels have prognostic value." (PMID 32938922, 2020). "Indeed, glucose starvation induced the overexpression of SLC7A11 and subsequent upregulation of glucose dependence for cell survival through the NRF2- and activating transcription factor 4 (ATF4)-dependent transcription in renal cancer cells." (PMID 33922165, 2021). "To confirm the upstream role of ER‐stress pathway during the renal cancer apoptosis, we assessed the effect of CHE after altering ATF4 levels in Caki cells." (PMID 31568643, 2020). "Norcantharidin (NCTD) exerts anti-tumor effects such as growth suppression, mitochondrial depolarization, and apoptosis induction in renal cancer cells through ER stress; this is accompanied by an increase in the expression of GRP78, p-elF2α, ATF4, and the CHOP protein in vivo and in vitro." (PMID 40002335, 2025). "Interestingly, pretreatment with the chemical chaperones (TUDCA and 4-PBA) and knockdown of CHOP and ATF4 by siRNA did not abolish combined treatment-induced apoptosis in renal carcinoma cells." (PMID 30356017, 2018).
renal fibrosis (8 papers, 2019 to 2025). A final common manifestation of a wide variety of chronic kidney diseases characterized by glomerulosclerosis and tubulointerstitial fibrosis. "QDD can alleviate renal fibrosis by inhibiting the PERK-eIF2α-ATF4 pathway and promoting autophagy in DN." (PMID 36091599, 2022). "We confirmed that QDD can indeed treat renal fibrosis by inhibiting the PERK-eIF2α-ATF4 pathway to promote autophagy in diabetic nephropathy." (PMID 36091599, 2022). "This study demonstrated that high glucose upregulated the PERK-eIF2α-ATF4 pathway, which in turn suppressed autophagy, resulting in renal fibrosis in DN." (PMID 36091599, 2022). "We demonstrated that QDD suppressed renal fibrosis in DN by inhibiting the PERK/eIF2α/ATF4 signaling pathway and restoring autophagy activity." (PMID 36091599, 2022). "The present study employed male mice as the experimental model, and thus the influence of ATF4 on glycolytic activity and renal fibrosis may differ across sexes." (PMID 41479926, 2025). "Therefore, we speculate that the mechanism of QDD delaying renal fibrosis in DN is related to the regulation of autophagy via the PERK/eIF2α/ATF4 signaling pathway." (PMID 36091599, 2022). "This study aimed to explore the effect of QDD in improving renal fibrosis in DN and the effect of QDD in regulating the PERK/eIF2α/ATF4 signaling pathway and renal autophagy." (PMID 36091599, 2022).
acute myeloid leukemia (7 papers, 2017 to 2025). Acute myeloid leukemia (AML) is a group of neoplasms arising from precursor cells committed to the myeloid cell-line differentiation. "In acute myeloid leukemia (AML), chemotherapeutic stress activates UPR transcription factors (e.g., XBP1 and ATF4), while lysosomal adaptation supports survival and ROS enhances genomic instability." (PMID 40723802, 2025). "Moreover, in acute myeloid leukemia JUN was recently found to be involved in the transcription of the UPR transcription factors XBP1 and ATF4." (PMID 29423023, 2018).
Burkitt lymphoma (7 papers, 2022 to 2024). A rare form of malignant mature B-cell non-Hodgkin lymphoma. "Overexpression of DNA damage-inducible transcript 3 (DDIT3/CHOP) in human glioblastoma, pancreatic, and Burkitt’s lymphoma cells links ATF4 to ferroptosis-associated diseases, such as Burkitt’s lymphoma and diabetic myocardial IRI." (PMID 39737174, 2024). "Artesunate (ART) enhances ferroptosis in Burkitt’s lymphoma cell lines by activating the ATF4/CHOP/CHAC1 pathway, an endoplasmic reticulum stress response." (PMID 38738174, 2024). "Activation of the ATF4-CHOP-CHAC1 pathway promotes ferroptosis in Burkitt’s lymphoma DAUDI and CA-46 cells." (PMID 35372041, 2022). "In addition, ART can activate the activating transcription factor 4- (ATF4-) C/EBP-homologous protein- (CHOP-) CHAC1 cascade in ERS to induce ferroptosis in Burkitt's lymphoma, and the activation process may be related to ROS production." (PMID 35028002, 2022). "In artesunate-induced ferroptosis in Burkitt’s lymphoma (BL) cells, CHAC1 is upregulated as part of the ATF4-CHOP-CHAC1 pathway activation." (PMID 39534397, 2024).
COVID-19 (7 papers, 2021 to 2025). A disease caused by infection with severe acute respiratory syndrome coronavirus 2. "Vice versa, IL10-signaling (which inhibits the IFN-response), chemokine receptor binding and ATF4-mediated ER stress response were increased in critical COVID-19." (PMID 33473155, 2021). "Analysis of the combined cohorts revealed elevated autoantibody responses against SPANXN4, STK25, ATF4, PRKD2, and CHMP3 proteins in COVID-19 patients." (PMID 37520825, 2023). "We then compared CD3+ cells isolated from COVID-19-infected subjects vs. healthy controls and found increased expression of activation markers including CD69, CD83, ICOS, RGS1 as well as other stress related genes including HIF1A, ATF4, NFKB1, and PR1." (PMID 36881624, 2023). "More importantly, the downregulation of redox-active genes, such as superoxide dismutase 3 (SOD3), activating transcription factor 4 (ATF4), and metallothionein 2A (M2TA), observed in the lungs of elderly COVID-19 patients seemed to be connected to the severity of the disease." (PMID 34202515, 2021).
heart failure (7 papers, 2017 to 2026). Inability of the heart to pump blood at an adequate rate to meet tissue metabolic requirements. "For instance, in a pressure overload-induced heart failure mice model, joint pathway analysis of transcriptomic and metabolomic data revealed that ATF4 preferably controlled oxidative stress and redox-related pathways." (PMID 41479926, 2025). "Activating Transcription Factor 4 (ATF4) has been established to be involved in cardiovascular diseases, such as heart failure and calcific aortic valve disease." (PMID 38913045, 2024). "ATF4 plays a critical role in the heart failure under conditions of hemodynamic stress by regulating the cytosolic and mitochondrial production of NADPH." (PMID 38913045, 2024). "WTAP has been proved to regulate the m6A modification of activating transcription factor 4 (ATF4) mRNA, promote ischemic myocardial injury by promoting neutrophil infiltration, endoplasmic reticulum stress and cardiomyocyte apoptosis, and finally lead to cardiac dysfunction and heart failure." (PMID 35811741, 2022). "Consistent with the increased heart-to-body-weight ratio of Polg-/mut; Tfam+/+ mice, the expression of Natriuretic Peptide A (Nppa), a marker for heart failure, and Mthfd2 a marker for OXPHOS dysfunction, were increased, whereas there was no change in mRNA levels for Atf4 and Atf5." (PMID 40587199, 2025).
intracerebral hemorrhage (7 papers, 2016 to 2024). A cerebrovascular disorder characterized by bleeding into one or both cerebral hemispheres including the basal ganglia and the cerebral cortex. "Studies have shown that Atf4 can increase the expression of the transcriptional activator Ddit3, thereby promoting apoptosis and reducing neuronal survival after intracerebral hemorrhage." (PMID 36497037, 2022). "In support of this notion, a recent paper showed that inhibition of ATF4 activation is protective in rodent models of intracerebral hemorrhage." (PMID 27307216, 2016). "Although CDNF was shown to regulate UPR initiated by transducers IRE1α, PERK and ATF6 in the pathological condition, we found that mRNA levels of UPR markers Grp78, spliced Xbp1, Atf4, and Chop were not significantly different between WT and Cdnf−/− mice after intracerebral hemorrhage." (PMID 36792604, 2023).
lung adenocarcinoma (7 papers, 2018 to 2026). A carcinoma that arises from the lung and is characterized by the presence of malignant glandular epithelial cells. "Significant enrichment of ATF4 target genes was detected in advanced lung adenocarcinomas with unfavorable prognosis, high risk of recurrence, and increased resistance to cisplatin." (PMID 38672243, 2024). "In human lung adenocarcinomas, increased expression of both p-eIF2α and ATF4 is mainly observed in advanced tumor subtypes with aggressive growth patterns, high risk of recurrence, and poor prognosis." (PMID 38672243, 2024). "The present study demonstrated that ATF4 transcriptionally activated Noxa in AD-treated lung adenocarcinoma cells." (PMID 33995110, 2021). "Therefore, we confirmed that ATF4 transcriptionally activated Noxa in AD-induced apoptosis of human lung adenocarcinoma cells." (PMID 33995110, 2021). "Moreover, ATF4 knockdown inhibited the upregulation of Noxa as well as AD-induced apoptosis in human lung adenocarcinoma cells." (PMID 33995110, 2021). "Additionally, we found increased protein expression of ATF4 and PHGDH, along with upregulated mRNA levels of PCK2, PHGDH, PSAT1, and PSPH, in DNM1L‐KO lung adenocarcinoma cell lines." (PMID 33152171, 2021).
schizophrenia (7 papers, 2014 to 2023). A major psychotic disorder characterized by abnormalities in the perception or expression of reality. "ATF4 is a transcription factor with multiple regulatory functions and whose polymorphisms have been associated with schizophrenia in male patients." (PMID 34197603, 2021). "For instance, ATF4 expression is correlated with general cognitive function in a gene-based association study and ATF4 expression level was found to be markedly reduced in the frontal cortex of human patients with schizophrenia." (PMID 37906604, 2023). "We speculate that insufficiency in the ATF4-Sig-1R pathway causes psychiatric symptoms in schizophrenia patients." (PMID 25032855, 2014). "Lastly, we attempted to pinpoint candidate downstream pathways of LTP in the context of schizophrenia by investigating the edges of ATF4 given its role as a key regulator of the LTP pathway." (PMID 34197603, 2021). "ATF4 is also decreased in the frontal cortex of schizophrenia patients and its binding to DISC1 (disrupted-in-schizophrenia 1) is compromised by schizophrenia-associated DISC1 mutations." (PMID 25071442, 2014). "Moreover, hippocampal ATF4 downregulation leads to defects in synaptic plasticity and memory and increases neuronal excitability by reducing GABA(B) receptor level, the deficit of which has been linked to a variety of neurological and psychiatric conditions, including schizophrenia." (PMID 37906604, 2023). "ATF4, an essential gene in the UPR triggered by ER stress, serves as a biomarker of schizophrenia." (PMID 37376599, 2023).
brain tumors (6 papers, 2019 to 2025). "ATF4 (activating transcription factor 4) is another protein that causes neuronal cell death and promote angiogenesis of primary brain tumors." (PMID 37335084, 2023). "In primary brain tumors, ATF4 activation promotes angiogenesis and neuronal cell death and leads to iron death in an xCT-dependent manner, which is consistent with the results in this chapter." (PMID 41249582, 2025). "illustrated that ATF4 prompted tumour proliferation, angiogenesis and malignancy of primary brain tumours via xCT/SLC7A11, a crucial regulator gene of the ferroptosis." (PMID 38652216, 2024).
head and neck squamous cell carcinoma (6 papers, 2013 to 2023). A squamous cell carcinoma that arises from any of the following anatomic sites: lip and oral cavity, nasal cavity, paranasal sinuses, pharynx, larynx, and salivary glands. "Furthermore, the ERAD-mediated ATF3/ATF4 complex binds to the NOXA promoter region to regulate NOXA transcription in mantle cell lymphoma and head and neck squamous cell carcinoma cells." (PMID 38039297, 2023). "In contrast, it was c-Myc but not ATF4 that transactivated Noxa to trigger cell apoptosis in head and neck squamous cell carcinoma cells after treated by MLN4924." (PMID 33995110, 2021). "That suggestion was supported by another study in which cisplatin-induced ATF3 in head and neck squamous cell carcinoma cells resulted in induction of apoptosis accompanied by an increased level of PMAIP1 through cooperative binding of ATF3 and ATF4 to the PMAIP1 promoter." (PMID 31296259, 2019).
injury (6 papers, 2017 to 2025). Damage inflicted on the body as the direct or indirect result of an external force, with or without disruption of structural continuity. "We recently showed ISRIB administration reversed mild head trauma-induced elevation in ATF4 protein." (PMID 33258451, 2020). "It has become increasingly evident that sustained activation of the UPR signaling pathways and upregulation of transcription factors, such as CHOP and ATF4, contribute to ER stress-induced liver injury." (PMID 32357187, 2020). "Studies have found that activating transcription factor 4 (ATF4) directly targets the activation of autophagy, and ATF4 expression is inhibited 48 h after LPS-induced acute liver injury." (PMID 31507440, 2019). "To investigate the physiological impacts of eIF2α-ATF4 regulation on ferroptosis, we employed a model of APAP-induced liver injury." (PMID 40227255, 2025).